TRIML1 (tripartite motif family like 1)
Description:
Probable E3 ubiquitin-protein ligase which plays an important role in blastocyst development.
Synonyms: RNF209; FLJ36180
Tractability: No criterion of Open Targets' tractability assessment is met for any kind of drug.
Gene: Protein-coding gene on chromosome 4 (188,139,441 to 188,147,743, forward strand). Ensembl gene ENSG00000184108.
Gene Ontology:
Molecular function: ubiquitin protein ligase activity
Biological process: innate immune response; protein ubiquitination
Cellular component: cytoplasm
Genetic constraint (gnomAD): Loss-of-function variants: 40 observed, 36.37 expected, observed/expected ratio (o/e) 1.1, 90% interval 0.85 to 1.43. The upper end of that interval is the gene's LOEUF score, 1.43, which puts it in group 5 of 6, group 1 being the genes least tolerant of losing a copy. Missense variants: 594 observed, 589.47 expected, observed/expected ratio (o/e) 1.01, 90% interval 0.94 to 1.08. Synonymous variants: 244 observed, 233.24 expected, observed/expected ratio (o/e) 1.05, 90% interval 0.94 to 1.16.
Homologues: Orthologues: chimpanzee TRIML1 (99% identical), macaque TRIML1 (96% identical), rabbit TRIML1 (88% identical), pig TRIML1 (84% identical), dog TRIML1 (84% identical), guinea pig TRIML1 (84% identical), rat Triml1 (81% identical), mouse Triml1 (80% identical). Paralogues in human: TRIM11 (36% identical), TRIM39 (35% identical), TRIM58 (34% identical), TRIM21 (34% identical), TRIML2 (33% identical), TRIM4 (32% identical), TRIM27 (31% identical), TRIM69 (29% identical), TRIM17 (28% identical), TRIM7 (28% identical), TRIM26 (28% identical), TRIM41 (28% identical), and 68 more.